PPARA (peroxisome proliferator activated receptor alpha)
Diseases named in the same sentence as PPARA in open-access papers (continued):
Sharing a sentence is not in itself a finding about the gene and the disease.
ovarian carcinoma (22 papers, 2011 to 2025). A malignant neoplasm originating from the surface ovarian epithelium. "For instance, in ovarian cancer, oleic acid not only activates PPARα to induce cell cycle progression but also accelerates glycolysis through the BRD4-L-MYC-GLUT axis to promote ovarian cancer cell proliferation and survival." (PMID 39984452, 2025). "PPARα agonists, such as fenofibrate and clofibrate, also show antitumor effects in several cancer types, including ovarian cancer." (PMID 39519311, 2024). "Yokoyama and co-workers reported an inhibition of proliferation in ovarian cancer cell lines in vitro, as well as a reduction in ovarian cancer cell tumor growth in vivo via the activation of PPARα with clofibrate." (PMID 35954274, 2022). "In favor of an anti-tumorigenic PPARα action, Yokoyama and colleagues reported that treatment with clofibric acid, a PPARα agonist, reduced ovarian cancer cell growth and tumor angiogenesis in xenotransplanted animals." (PMID 32785018, 2020). "Furthermore, the expression level of PPARα was negatively correlated with the overall survival rate of patients with ovarian cancer." (PMID 39519311, 2024). "Together with the increased PPARα expression in ovarian CSCs, these results suggest that PPARα may be responsible for the poor prognosis in patients with ovarian cancer." (PMID 39519311, 2024). "Finally, treatment with WY14,643 in the presence of PPARα-tr resulted in the significant reduction of cell viability of AML12 and human ovarian cancer cell line, SKOV3." (PMID 26122096, 2015).
autoimmune disease (21 papers, 2008 to 2025). A disorder resulting from loss of function or tissue destruction of an organ or multiple organs, arising from humoral or cellular immune responses of the individual to their own tissue constituents. "Studies on other autoimmune diseases and liver inflammation-related diseases have confirmed that PPARα and PPARγ have regulatory effects on NKT cells." (PMID 35880178, 2022). "Proof-of-concept studies are needed to assess efficacy and safety of PPARα agonists in autoimmune diseases including RA and to address the issues arising from our current understating of PPARα agonists pharmacology." (PMID 21760804, 2011). "Although the information regarding the role of PPARs in autoimmune diseases is limited, the available data suggests that activation of PPARs, especially PPARα, may restrict the development of autoimmune diseases." (PMID 37928539, 2023). "This specific regulation of immune deviation made these PPARα agonists very attractive candidates to be used therapeutically in treating Th1-mediated autoimmune diseases, including MS, in addition to their excellent track history as oral agents used to treat hypertriglyceridemia." (PMID 21234105, 2010). "PPARα could potentially serve as a molecular target for the treatment of autoimmune diseases." (PMID 38398835, 2024). "The potential relationship between differences in PPARα expression in CD4+ T cells and characteristics of autoimmune diseases remains to be investigated." (PMID 35880178, 2022).
schizophrenia (21 papers, 2012 to 2024). A major psychotic disorder characterized by abnormalities in the perception or expression of reality. "The gene encoding for PPARα (PPARA) was found to be downregulated in hair follicle cells from schizophrenia patients, further showing an association between PPARα and this psychiatric condition." (PMID 34681249, 2021). "The evidence for this derives from preclinical studies with the maternal immune activation (MIA) model or the postnatal lesional model and from clinical investigations into the association of schizophrenia with PPARα genes." (PMID 34681249, 2021). "Based on next-generation sequencing (NGS) analysis, c.209-2delA, His117Gln, Arg141Cys, and Arg226Trp of the PPARA gene were found to be risk variants for schizophrenia in 1200 Japanese patients with schizophrenia." (PMID 34833044, 2021). "Our study confirms previous evidence that females are less susceptible to MIA and highlights PPARα as a potential target for treatments in schizophrenia." (PMID 30461214, 2019). "A recent study in Japanese patients with schizophrenia identified several PPARA variants with reduced functionality, which may increase the risk of developing psychotic symptoms." (PMID 35625650, 2022). "The decrease in PPARα expression is associated with the development of schizophrenia." (PMID 35269952, 2022). "In support of this hypothesis, several animal models of PPARα deficiency show endophenotypes that resemble symptoms of schizophrenia in humans." (PMID 35625650, 2022). "Additionally, a study on a Croatian population investigated whether a functional L162V polymorphism in the PPARα gene was also associated with schizophrenia risk." (PMID 34681249, 2021). "The role of PPARα in the development of schizophrenia is also supported by the positive effects of PPARα agonist administration, in a study conducted in a neurodevelopmental model of this disorder." (PMID 35625650, 2022). "Pharmacological stimulation of PPARα rescues the endophenotypes of schizophrenia in several KO mouse models." (PMID 35625650, 2022). "Consistent with the notion that schizophrenia displays a pro-inflammatory phenotype, genes involved in inflammation have been found to be affected, including decreased PPARα mRNA levels and increased IL-6 and TNFα." (PMID 34681249, 2021). "In schizophrenia, the expression of PPARγ could be increased while PPARα is downregulated, suggesting a metabolic-inflammatory imbalance in its pathogenesis." (PMID 35269952, 2022). "Recent studies have shown that PPARα may modulate the neuroinflammatory mechanisms observed in psychiatric diseases, such as depression and schizophrenia." (PMID 35269952, 2022). "Furthermore, behavioral deficits and impaired synaptogenesis in the cerebral cortex similar to schizophrenia were seen in Pparα knockout mice." (PMID 34833044, 2021). "PPARα seems to be critically involved in the pathophysiology of schizophrenia." (PMID 34681249, 2021). "Peroxysome Proliferator-Activated Receptors α (PPARα) could be other interesting targets for reducing oxidative stress in schizophrenia." (PMID 22966448, 2012). "Thus, PPARα agonists could play an interesting role in decreasing the neuroinflammation observed in schizophrenia." (PMID 35269952, 2022). "In schizophrenia, the WNT/β-catenin pathway and the expression of PPARα act in a positive interplay, which in turn leads to this complex negatively interacting with the expression of PPARγ." (PMID 35269952, 2022). "In schizophrenia, the expression of PPAR-γ is increased, whereas the WNT/β-catenin pathway and PPARα are downregulated." (PMID 35269952, 2022). "In an additional independent sample set (control, n=55; schizophrenia, n=42), the findings for PPARA and PPARB/D were replicated, thus suggesting that these nuclear receptor genes are involved in the pathophysiology of schizophrenia." (PMID 28872641, 2017).
schizophrenia (continued). "The current findings showing that expression of RXRA, PPARA and PPARB/D is abnormally reduced in the hair-follicle cells of patients with schizophrenia not only support their putative role in schizophrenia pathogenesis but also suggest that this measure is a potential biomarker for schizophrenia." (PMID 28872641, 2017). "However, no other studies have further addressed the effect of PPARα agonists using this specific model of schizophrenia." (PMID 35625650, 2022).
renal cell carcinoma (20 papers, 2009 to 2025). "The levels of PPARα protein were associated with RCC invasiveness in two renal cell carcinoma cell lines (AKI-1 and 786-O)." (PMID 38189049, 2023). "Interestingly, PPARα regulates FAO activity to meet the higher energy requirements of high-grade renal cell carcinoma (RCC) compared with low-grade RCC." (PMID 38189049, 2023). "However, using only one ccRCC cell line for analyzing is the limitation in our research, so we intend to apply more renal cell carcinoma cell lines such as Caki-2 or UM-RC-2 for validating the roles of PPARα in different pathological patterns of RCC." (PMID 33959154, 2021). "Furthermore, blocking PPARα in renal cell cancer cell lines under the synergistic effect of glycolytic inhibition significantly reduced the levels of the cell cycle-related proteins cyclin D1 and CDK4, and blocked the cell cycle in the G0/G1 phase, thereby reducing cell viability." (PMID 37251321, 2023). "Similarly, Abu Aboud and colleagues demonstrated enhanced apoptosis in renal-cell carcinoma upon PPARα inhibition in vitro and in vivo through a decrease in enhanced fatty-acid oxidation and oxidative phosphorylation, and further cancer-cell-specific glycolysis inhibition." (PMID 35954274, 2022). "PPARα may be one of the potential targets for treating renal cell carcinoma." (PMID 33959154, 2021). "The PPARα antagonist GW6471 attenuated enhanced fatty-acid oxidation and oxidative phosphorylation, blocked enhanced glycolysis, and reduced tumor growth in a renal-cell carcinoma model in nude mice." (PMID 35954274, 2022). "It has been shown that both PPARα pharmacological antagonism and siRNA‐mediated PPARα KD reduce the expression of c‐Myc, cyclin D1 and CDK4 in renal cell carcinoma (RCC) in vitro models." (PMID 30565681, 2019).
viral infection (20 papers, 2017 to 2025). "SARS-CoV-2 inhibition of PPARα-dependent lipid oxidation is surprising, as the pathway was up-regulated in other viral infections." (PMID 36705566, 2023). "The still scarce, but gradually emerging experimental data indicate that PPARα affects the innate host response to viral infections." (PMID 34638886, 2021). "Viral infection that was induced prior to challenge with S. aureus led to increased PPARα expression in lungs." (PMID 34638886, 2021). "We initially examined PPARα since potential antiviral and immunomodulatory activity of PPARα agonists during viral infection have been reported, and PPARα agonists have been reported to reverse IFN refractoriness during flaviviral infection." (PMID 28265266, 2017). "Interestingly, certain viral infections, such as Zika virus, have been shown to modulate and dysregulate PPARα signaling pathways in human cells." (PMID 35003101, 2021). "It appears that PPARα activation and an increase in viral load and pathogenesis are heavily correlated, again showing an inverse relationship between bacterial infection prognosis and viral infection prognosis." (PMID 35003101, 2021).
Anxiety (19 papers, 2019 to 2025). Intense feelings of nervousness, tension, or panic often arise in response to interpersonal stresses. "The introduction of PPARα agonists reduces the accumulation of Aβ peptide, improves memory, and reduces anxiety in APP-PSEN1ΔE9 mice (AD model)." (PMID 35457077, 2022). "Studies have noted that PPARα regulates the malignant behaviors of tumor cells by targeting CPT1C, and PPARα activation can alleviate the amyloidosis and reverse memory deficits and anxiety in AD." (PMID 34424821, 2021). "Peroxisome proliferator-activated receptors (PPARs) are nuclear receptors with three isoforms (PPARα, PPARβ/δ, PPARγ) and can regulate pain, anxiety, and cognition." (PMID 32102354, 2020). "As such, Δ9-THC may produce anxiety by activating PPARγ and PPARα in both GABA and glutamate neurons in the amygdala." (PMID 36909477, 2023). "However, the role of PPARα or PPARβ/δ in modulating anxiety or fear responses remains unexplored." (PMID 32102354, 2020). "Activation of PPARg inhibits DA-dependent oICSS, while blockade of PPARa and PPARg attenuates Δ9-THC-induced reward-attenuation (aversion) and anxiety but potentiates Δ9-THC-induced hypoactivity and catalepsy." (PMID 36909477, 2023). "Activation of PPARγ inhibits DA-dependent oICSS, while blockade of PPARα and PPARγ attenuates Δ9-THC-induced reward-attenuation and anxiety but potentiates Δ9-THC-induced hypoactivity and catalepsy." (PMID 37479780, 2023). "However, whether PPARβ/δ and PPARα modulate anxiety or fear remains unexplored." (PMID 35335382, 2022). "Only one recent study has investigated the effect of PEA on anxiety-related behaviour and showed that chronic administration of PEA increased exploration time in the OF test, an effect blocked by the PPARα antagonist MK886." (PMID 34072060, 2021). "It was demonstrated that activation of Peroxisome proliferator activated receptor alpha (PPARA/PPARα) which is involved in fatty acid metabolism and in autophagy activation, decreased amyloid pathology and reversed memory deficits and anxiety symptoms in APP-PSEN1ΔE9 mice." (PMID 41123674, 2025). "We note that PPARα/γ agonists or antagonists alone failed to alter basal anxiety levels, while PPARα or PPARγ antagonism only partially reduced Δ9-THC-induced anxiety." (PMID 37479780, 2023). "Another important finding in this report is that antagonism of PPARα and PPARγ attenuated Δ9-THC-induced anxiety, implicating these receptors in the negative affective properties of cannabinoids." (PMID 36909477, 2023). "Moreover, the blockade of PPARα, PPARβ/δ, and PPARγ in the BLA increased innate anxiety status in the absence of pain in NFC rats." (PMID 35335382, 2022). "Moreover, while PPARβ/δ and PPARγ blockade or PEA did not modulate pain, cognition- or anxiety-related behaviour, blockade of PPARα exacerbated the CFA-induced impairment of spatial memory and tended to increase anxiety-related responses in the LDB test without affecting mechanical hypersensitivity." (PMID 34072060, 2021).
acute kidney injury (18 papers, 2010 to 2025). Sudden and sustained deterioration of the kidney function characterized by decreased glomerular filtration rate, increased serum creatinine or oliguria. "CypD binds peroxisome proliferator-activated receptor alpha (PPARα) and reduces PPARα activity to downregulate fatty acid β-oxidation in cisplatin acute kidney injury." (PMID 39456250, 2024). "In renal failure, activation of PPARα using WY-14,643 can avoid acute tubular necrosis by promoting fatty acid oxidation." (PMID 36384580, 2022). "By increasing peroxisome function, SIRT1 activation, which is reciprocally stimulated by upregulated PPARα and PPARδ, can prevent the drug-induced renal cell apoptosis and acute kidney injury in mice." (PMID 31321239, 2019). "Perilipin 2 impacts acute kidney injury via regulation of PPARα." (PMID 38379702, 2024). "Although a role for PPARα in reducing renal injury and PPARα ligands could attenuate cisplatin-induced acute renal failure (ARF) was reported in animal models, its exact mechanisms are still inconclusive." (PMID 21076544, 2010). "Recently, PPARα activation has been shown to confer additional benefits on endothelial function, kidney function, and anti-inflammation, suggesting that PPARα agonists may be good candidates for treating acute renal failure." (PMID 21076544, 2010). "PPARα-mediated FAO has been suggested to play an important regulatory role in the pathogenesis of acute kidney injury (AKI)." (PMID 35308207, 2022). "Therefore, it is interesting to investigate whether PPARα modification, including phosporylation, SUMOylation, and ubiquitination, is involved in inflammation-induced renal failure." (PMID 21076544, 2010). "Activation of PPARα with ligands such as fibrate or WY14643 reduces cisplatin and I/R-induced acute kidney injury." (PMID 21076544, 2010).
Cerebral ischemia (18 papers, 2012 to 2025). Restriction of arterial blood supply to the brain associated with insufficient oxygenation to support the metabolic requirements of the tissue. "This study aims to further clarify the role of PPARα in astrocyte inflammation activation after cerebral ischemia and to explore the underlying mechanism." (PMID 36979952, 2023). "In this study, we found that reduced PPARα expression was shown to be associated with astrocyte inflammation activation after brain ischemia." (PMID 36979952, 2023). "Therefore, the lack of Fasudil-induced neuroprotection in PPARαKO mice after cerebral ischemia may be attributed to PPARα loss-of-function, decreased SOD expression, and increased ROS concentration." (PMID 38055403, 2023). "The predominance of upregulated downstream targets (red nodes) suggests that TNFα drives a pro-inflammatory transcriptional program following brain ischemia and that PPARα normally suppresses this response." (PMID 40362325, 2025). "For instance, in some experimental models of retinal or brain ischemia, PPARα activation appeared to reduce ROS production by repressing genes like the NADPH oxidase-4 (Nox4)." (PMID 41301903, 2025). "The present study aimed to investigate the neuroprotective effects of OEA on peroxisome proliferator-activated receptor α (PPARα)-mediated microglia M2 polarization after cerebral ischemia." (PMID 37111378, 2023). "All these results indicate that PPARα dysfunction augmented the astrocyte activation and delayed the recovery of motor function after brain ischemia." (PMID 36979952, 2023). "All these results demonstrate the important role of PPARα in inhibiting the neuroinflammation that occurs during the chronic phase of brain ischemia." (PMID 36979952, 2023). "Our results showed that PPARα was mainly expressed in activated astrocytes during the chronic phase of brain ischemia and PPARα dysfunction promoted astrocyte inflammatory activation." (PMID 36979952, 2023). "Recently, we have found that OEA inhibits astrocyte activation after brain ischemia by activating PPARα." (PMID 36979952, 2023). "All these results indicate that PPARα dysfunction promotes astrocyte over-activation after transient brain ischemia." (PMID 36979952, 2023). "Firstly, we found that a PPARα deficit promotes astrocyte inflammation activation and retards motor function recovery after brain ischemia." (PMID 36979952, 2023). "All these findings prompt us to explore the role of PPARα in the modulation of autophagy during the astrocyte inflammatory activation that occurs after brain ischemia." (PMID 36979952, 2023). "PPARα-null mice exhibit an aggravated reaction to brain ischemia and delay the recovery of motor function." (PMID 36979952, 2023). "Although others’ reports have indicated that PPARα-null mice show increased infarct volumes after brain ischemia, our study provides new evidence that PPARα null promotes astrocyte inflammation activation and glial scar formation after brain ischemia." (PMID 36979952, 2023). "These in vivo data were in concordance with in vitro BBB results suggesting contribution of PPARα independent mechanisms as well as PPARα dependent PAI-1 regulation to multifaceted effects of WY-14643 during cerebral ischemia." (PMID 28603485, 2017). "The authors thus concluded that PPARα's neuroprotective effects in cerebral ischemia were due to alleviation of ischemia-induced oxidative stress and inflammation and improved cerebral microvascular function." (PMID 25705219, 2015). "Expression of PPARα mRNA in the rat hippocampus increased in the group with reperfusion for 30 min after global cerebral ischemia." (PMID 23304113, 2012). "An experimental study indicated that oleuropein (OLE), the main constituent of Olea europea leaf extracts, activated PPARα in neurons and astrocytes of wild-type mice, providing neuroprotection against noxious biological reactions that are induced following cerebral ischemia." (PMID 41301903, 2025).